CAMK2N2 (calcium/calmodulin dependent protein kinase II inhibitor 2)
Description:
Potent and specific cellular inhibitor of CaM-kinase II (CAMK2). Traps Ca(2+)/calmodulin on CAMK2 (By similarity).
Synonyms: CaM-KIIN; CAMKIIN
Tractability: No criterion of Open Targets' tractability assessment is met for any kind of drug.
Gene: Protein-coding gene on chromosome 3 (184,259,213 to 184,261,553, reverse strand). Ensembl gene ENSG00000163888.
Subcellular location: Nucleus; Cytoplasm, cytosol; Synapse
Subcellular location (Human Protein Atlas): Nucleoplasm; Basal body; Centrosome
Gene Ontology:
Molecular function: calcium-dependent protein kinase inhibitor activity; protein kinase binding; protein kinase inhibitor activity
Cellular component: nucleus; synapse; cytosol
Genetic constraint (gnomAD): Loss-of-function variants: 3 observed, 7.02 expected, observed/expected ratio (o/e) 0.43, 90% interval 0.19 to 1.1. That is too few expected variants to judge how well the gene tolerates losing a copy. Missense variants: 85 observed, 102.62 expected, observed/expected ratio (o/e) 0.83, 90% interval 0.69 to 0.99. Synonymous variants: 45 observed, 42.62 expected, observed/expected ratio (o/e) 1.06, 90% interval 0.83 to 1.35.
Homologues: Orthologues: chimpanzee CAMK2N2 (100% identical), macaque CAMK2N2 (100% identical), pig CAMK2N2 (100% identical), dog CAMK2N2 (99% identical), mouse Camk2n2 (99% identical), rabbit CAMK2N2 (99% identical), rat Camk2n2 (99% identical), tropical clawed frog camk2n2 (76% identical), zebrafish camk2n1a (73% identical), zebrafish camk2n2 (73% identical). Paralogues in human: CAMK2N1 (65% identical).
Diseases named in the same sentence as CAMK2N2 in open-access papers:
CAMK2N2 is named in the same sentence as 9 diseases in open-access papers, as found by Europe PMC text mining. Sharing a sentence is not in itself a finding about the gene and the disease. The quoted sentences say what the papers report.
Hypertension (1 paper, 2020). The presence of chronic increased pressure in the systemic arterial system. "Although numerous ncRNAs were shown to regulate WNT/β-catenin signaling in various cell types, and a few lncRNAs and miRNAs were recently linked to coronary heart disease and hypertension, the potential regulation of WNT3 and CAMK2N2 expression by ncRNAs in EH remains undefined." (PMID 32392180, 2020). "Importantly, our research also highlights a potentially critical role for the lncRNA LOC646616 in the activation of the WNT/β-catenin pathway by relieving the negative regulation exerted by miR-637 on both WNT3 and CAMK2N2 expression in human vascular smooth muscle cells during hypertension." (PMID 32392180, 2020). "Therefore, we propose that by releasing miR-637-mediated inhibition of both WNT3 and CAMK2N2 expression, LOC646616 upregulation in hypertension promotes WNT/β-catenin pathway activation both directly, through enhanced WNT3 expression, and indirectly, by preventing CAMKII-mediated inhibition." (PMID 32392180, 2020).
infection (1 paper, 2017). The state of being infected such as from the introduction of a foreign agent such as serum, vaccine, antigenic substance or organism. "After infection of dorsal hippocampi with control or CaMK2N2-expressing rAAVs, mice were conditioned and tested for contextual fear LTM after one day followed by a second LTM test 4 days after conditioning." (PMID 28642476, 2017).
CAMK2N2 also shares sentences with these, for which no sentence is quoted: myocardial infarct (2 papers); heart disease (1); heart failure (1); ischemia (1); myeloid leukemia (1); myeloproliferative disorder (1); Stroke (1).